OXTR (oxytocin receptor)
Diseases named in the same sentence as OXTR in open-access papers (continued):
Sharing a sentence is not in itself a finding about the gene and the disease.
Paranoia (1 paper, 2024). The feeling and belief that one is being targeted or is a focus of negative or untoward actions, overt or covert, from others. "This attachment failure and the ensuing paranoia may be moderated by genetic factors, including polymorphisms in the oxytocin receptor gene." (PMID 38388569, 2024).
pulmonary tuberculosis (1 paper, 2020). A bacterial infection that affects the lungs and is caused by Mycobacterium tuberculosis. "Among our reference cohort datasets, OXTR is most highly increased in patients with S. aureus infection or active pulmonary tuberculosis." (PMID 32736569, 2020).
substance abuse (1 paper, 2025). The use of a drug for a reason other than which it was intended or in a manner or in quantities other than directed. "In Black men, advantageous ties with peers, parents, and partners were inversely associated with DNA methylation at OXTR, a gene encoding the oxytocin receptor, leading to less substance abuse." (PMID 39964583, 2025).
tobacco use disorder (1 paper, 2025). "Naturally, the study has several limitations, some of which we have already discussed in another study on oxytocin and OXTR methylation in tobacco use disorder." (PMID 40658054, 2025).
tuberous sclerosis complex (1 paper, 2020). "We studied sleep duration in three mouse models by means of home-cage monitoring: Tsc2+/− (tuberous sclerosis complex), oxytocin receptor (Oxtr) knockout (KO) (autism spectrum disorders), and Shank3 e4-9 KO (Phelan–McDermid syndrome)." (PMID 33396736, 2020).
Ventricular arrhythmia (1 paper, 2018). "Importantly, intravenous administration of the oxytocin receptor antagonist, retosiban, completely prevented the MI-induced increase in cardiac SNA, which likely contributed to the reduced incidence of ventricular arrhythmias and improve survival." (PMID 30320228, 2018).
psychiatric disorder (37 papers, 2012 to 2025). A disorder characterized by behavioral and/or psychological abnormalities, often accompanied by physical symptoms. "The study discovered that individuals who received less maternal care during childhood exhibit significantly higher methylation of OXTR during adulthood, which is significantly associated with the incidence of psychiatric disorders." (PMID 38191308, 2024). "Variations in the OXTR gene (e.g., OXTR gene polymorphisms) have been proven to be associated with a variety of psychiatric disorders or alterations in brain function in humans." (PMID 37153633, 2023). "Overall, while some research questions involved in OXT/OXTR deficiency-related psychiatric disorders have been answered, many others remain to be addressed." (PMID 37153633, 2023). "DNA methylation of the oxytocin receptor gene has been shown to be linked to social behaviour, emotional behaviour and psychiatric diseases." (PMID 34713517, 2021). "Additional studies with adequate methodology are needed to explore the relation between OXTR polymorphism and these socially related psychiatric disorders." (PMID 26121678, 2015). "Recent findings have shown that experiences in early life can epigenetically tune the expression of OXTR, which has been associated with psychiatric disorders and individual differences, including impairments in social recognition and autistic-like behaviors in neural response to social stimuli." (PMID 33134294, 2020). "The present article sought to explore the question whether a polymorphic variation of the OXTR coding gene could be associated with differential susceptibility to psychiatric disorders." (PMID 22510359, 2012). "Here we summarize the expression of OXTR and the involvement of OXT/OXTR signaling in the regulation of intracellular effects, behavioral responses, functional alterations, and the outcomes of OXTR dysregulation or deficiencies in behavioral deficits and psychiatric disorders." (PMID 37153633, 2023). "The OXTR gene, which encodes the OXT receptor, a major player in OXTsignaling, has been associated with various psychiatric disorders and social cognitionthrough genetic association analysis." (PMID 39606181, 2024). "We hope that this review can provide a deep insight into the study of OXTR-involved psychiatric disorders." (PMID 37153633, 2023). "Genetic variations of the OXTR gene, including the most common SNPs, have been found in human psychiatric disorders." (PMID 37153633, 2023). "Nonetheless, here, we summarized the aberrant OXT/OXTR signaling in the pathogenesis of the following psychiatric disorders or alterations in brain function." (PMID 37153633, 2023). "Given the significance of these new findings, in this review, we focus on the progress of OXTR's functions, intrinsic mechanisms, and its correlations with psychiatric disorders or deficits in behaviors." (PMID 37153633, 2023). "A clear pattern of OXTR gene expression in the developing brain was found in postmortem human brain samples, with OXTR expression increasing during the prenatal period, peaking in early childhood, and strong spatiotemporal coupling to psychiatric disorders." (PMID 38017588, 2023). "Dysregulation of the OXTR gene in a variety of psychiatric disorders has enabled researchers to investigate the epigenetic state of OXTR in psychiatric patients." (PMID 37153633, 2023). "With regard to its important roles in psychiatric disorders, OXTR has been investigated in other aspects related to abnormal behaviors and aberrant brain structure and function." (PMID 37153633, 2023). "We focused on oxytocin structure, distribution, genetics, and the oxytocin receptor system, as well as the relationship of oxytocin with other neurotransmitters and the resulting impacts on the main psychiatric disorders." (PMID 35888641, 2022). "One commonly studied biomarker for oxytocin involvement in psychiatric diseases is DNA methylation at the oxytocin receptor gene (OXTR)." (PMID 33516250, 2021).
psychiatric disorder (continued). "Many studies have demonstrated a link between CD38 rs3796863 and OXTR rs53576 polymorphic regions and psychosocial characteristics as well as various psychiatric disorders in adolescents." (PMID 34434131, 2021). "Oxytocin and OXTR are closely related to childbirth and lactation, and they also play important roles in the treatment of some psychiatric diseases." (PMID 32706026, 2020). "The role of epigenetic OXTR regulation via DNA methylation in psychiatric disorders such as OCD is a promising and relatively new field of investigation." (PMID 32631409, 2020). "Taking into account the complexities and challenges in the field of psychiatric disorders that we are facing, additional studies need to be conducted for a better understanding of how the OXTR gene variations happen and how those variations affect the psychiatric phenotypes." (PMID 37153633, 2023). "The review summarizes the aberrant OXT/OXTR signaling in behavioral deficits and psychiatric disorders, contributing to the understanding of the neurobiology of psychiatric disorders and providing insights into the progress of OXTR-related neurodevelopmental disorders." (PMID 37153633, 2023). "Altogether, the evidence may support the roles of epigenetic and genetic changes in the OXTR gene in the development of many psychiatric disorders and the structural and functional abnormalities in the brain." (PMID 37153633, 2023). "Although the mechanisms underlying the aggression involved in psychiatric disorders remain unclear, emerging evidence showed the involvement of the OXT/OXTR signal in aggression." (PMID 37153633, 2023). "Summary of aberrant OXTR in psychiatric disorders and alterations of brain volumes." (PMID 37153633, 2023). "The study’s authors speculate on the potential utility of oxytocin receptor agonists in the treatment of stress-related psychiatric disorders in adulthood." (PMID 35888641, 2022). "Fifthly, we cannot conclude whether the epigenetic OXTR alterations reflect specific OCD factors or shared traits with other psychiatric disorders related to socio-emotional problems and repetitive behaviors." (PMID 32631409, 2020). "Thirdly, the OXTR SNP rs237897 was significantly associated with Anxious Attachment in both Caucasians and non-Caucasians who did not report a history of mental illness." (PMID 30393594, 2018). "Recent studies have identified that oxytocin (OT) and the oxytocin receptor (OXTR) exert important roles in the regulation of complex social behaviors such as maternal behavior, mating, aggression, attachment, sexual behavior, as well as in psychiatric disorders characterized by social deficits." (PMID 33134294, 2020). "The abnormal DNAm status of OXTR was also uncovered in other neurodevelopmental disorders, especially in ASD, showing that OXTR DNAm patterns were altered in many psychiatric disorders." (PMID 37153633, 2023). "To demonstrate the utility of BECon, we assessed key candidate genes often investigated for changes in DNAm in relation to psychiatric disorders (BDNF, COMT, OXTR and DRD4)." (PMID 28763057, 2017). "Epigenetic non-structural changes in the OXTR gene, such as DNA methylation that may mediate gene expression, are commonly found in psychiatric disorders." (PMID 37153633, 2023). "OXTR is widely expressed in different functional brain regions, including PFC, hippocampus, amygdala, and hypothalamus, exerting important roles in the regulation of complex social behaviors, as well as in psychiatric disorders characterized by social deficits." (PMID 33134294, 2020). "Two OXTR SNPs, rs2254298 and rs53576, wereexamined independently for their association with OSA symptoms because they havebeen most commonly reported to be associated with psychiatric disorders and socialbehaviors and are not in linkage disequilibrium with each other." (PMID 39606181, 2024).
psychiatric disorder (continued). "Firstly, in both the Caucasian samples with and without a history of mental illness, sociosexual orientation was found to be significantly related to variation in dopamine DRD1 rs265981 and oxytocin OXTR rs237887." (PMID 30393594, 2018).
cancer (26 papers, 2003 to 2025). A tumor composed of atypical neoplastic, often pleomorphic cells that invade other tissues. "WPOI 4-5-derived cancer-associated fibroblasts (CAFsWPOI4-5), characterized by high oxytocin receptor expression (OXTRHigh), contribute to local-regional metastasis." (PMID 36045118, 2022). "Among the differentially expressed IRGs, we identified 5 IRGs (CD1B, XCL1, PLCG2, NGF, and OXTR) for inclusion in the risk score, and previous studies have indicated that these genes were related to immune processes and cancer progression." (PMID 32508884, 2020). "Therefore, the distress caused by poisoning oxytocin receptor in dams imprints shorter life span, increased cancer risk and higher tumorigenic capacity of BMCs in later generations." (PMID 35546267, 2023). "Even though our results showed a low expression of OXTR in high metastatic patients, the previous studies explored that its overexpression is associated with increased cell migration and the proliferation of cancer cells via the pSTAT5 pathway." (PMID 36430579, 2022). "OXTR belongs to the G-protein-coupled receptor class A/rhodopsin family and plays a pivotal role in social bonding, stress response, maternal behavior, sexual activity, uterus contraction, milk ejection, and cancer." (PMID 38979515, 2024). "In addition, in human patients with UC and patients with colitis-associated cancer, the expression of B3GNT7 was decreased and positively correlated with OXTR." (PMID 38979515, 2024). "The involvement of OXTR in cancer development was suggested several times." (PMID 36835321, 2023). "Interestingly, the use of data related to OXTR was proposed for prognostic purposes in different cancers." (PMID 36835321, 2023). "Increased levels of OXTR mRNA were correlated with the occurrence of other cancers." (PMID 36835321, 2023). "However, the role of OXT/OXTR signaling in different cancers seems to be inconsistent." (PMID 36045118, 2022). "In our study, we identified six signature genes, namely TNFRSF11B, METTL7B, SSTR2, OXTR, CDKN2C, and H19 which have been extensively studied in the past and are known to play a significant role in cancer." (PMID 37713112, 2024). "Additionally, the cancer progression and chemoresistance-related OXT/OXTR (oxytocin) genes were highly expressed between CAFs and the neoplastic cells." (PMID 37633924, 2023). "From the differential genes involved in these pathways, we identified several gene clusters uniquely upregulated in the CAFWPOI 4-5 type; neuronal development and function-related (RELN, MYH10, CACNB4, OXTR, CAV3, CHRM2) and inflammation and cancer-related (RELN, IL21R, EDNRB, CAV3, OXTR)." (PMID 36045118, 2022). "Furthermore, the down-regulation of OXTR observed in CAC may be mediated by elevated levels of inflammatory cytokines, which are prevalent in chronic inflammation and cancer." (PMID 38979515, 2024). "The cyclic neuropeptide oxytocin (OT) elicits a plethora of biological responses via the oxytocin receptor (OTR) in both the central and peripheral nervous system, including social bonding, stress, maternal behaviour, sexual activity, uterus contraction, milk ejection and cancer." (PMID 32782397, 2020).
tumor (26 papers, 2003 to 2025). "In vivo, we found that mice co-injected with OXTRHigh CAFs and HN6 tumor cells had a more significant tumor burden and increased metastasis to lymph nodes than OXTRHigh CAFs deficient in OXTR." (PMID 36045118, 2022). "To confirm that OXTR mRNA level is associated with tumor progression and poor prognosis in patients, we utilized ROC curves." (PMID 34877409, 2021). "Multi-omic profiling of cabazitaxel-refractory tumors uncovered oxytocin-receptor (OXTR) signalling as a tumor-cell niche." (PMID 40806607, 2025). "For example, the TJP2 and OXTR genes showed haplotype-biased methylation upregulation, resulting in the downregulation of their mRNAs in the tumor regions." (PMID 41187747, 2025). "To investigate a putative role for OXTR expression in CAFWPOI4-5-dependent OSCC tumor invasion, we performed a transcriptomic profiling analysis of different OSCC patients-derived CAFs with high or low OXTR levels." (PMID 36045118, 2022). "The transcriptional levels of OXTR in some adjacent normal tissues and tumor tissues were analyzed using TIMER." (PMID 34877409, 2021). "Compared with normal tissues, OXTR mRNA level was higher in COAD tissues, which was associated with tumor progression." (PMID 34877409, 2021). "In order to investigate the role of upregulated OXTR mRNA in COAD patients, we further analyzed the relationship between OXTR mRNA levels and tumor progression." (PMID 34877409, 2021). "Oxytocin receptors (OTR) have been described in a number of tumours of different origin, and represent a new target for specific radiolabelled oxytocin (OT) analogues in cancer diagnosis and therapy." (PMID 12942128, 2003). "Oxytocin inhibits tumor growth, often through the oxytocin receptor." (PMID 41301028, 2025). "Moreover, the simultaneous activations of OXTR and fucosylation by l-fucose significantly alleviated tumor burden." (PMID 38979515, 2024). "LEP, ADIPOQ, and OXTR manifest lower expression in tumor samples." (PMID 27857161, 2016). "Furthermore, the variant frequencies in the tumor of five mutations within the OXTR, TBX21, CSPP1, and PTPN21 genes ranged from 40%–50% in the primary tumor, thus suggesting the likelihood that these were present in virtually all tumor cells at the onset (heterozygosity)." (PMID 26527318, 2016). "Here the authors show that a fibroblast subset characterized by the expression of the oxytocin receptor is enriched in highly invasive WPOI 4-5 OSCC tumors and can be targeted to reduce the desmoplastic stroma and tumor metastasis." (PMID 36045118, 2022). "OXTRHigh CAFs are rich in the WPOI 4–5 type stroma and promote ECM remodeling through ERK5 signaling, which, in turn maintains OXTR and CCL26 expression, correlating with an invasive tumor phenotype." (PMID 36045118, 2022). "In this work, we show that a stromal fibroblast cluster characterized by high expression of oxytocin receptor (OXTR) contributes to sustain the desmoplastic and mesenchymal phenotype of WPOI 4–5 tumor by upregulating nuclear ERK5 signaling." (PMID 36045118, 2022). "This study lacks animal experiments and test results of OXTR protein in COAD tissue, so it is impossible to directly verify the influence of OXTR on COAD tumor growth, which is the limitation of this study." (PMID 34877409, 2021). "Five tumor suppressors or suppressor candidates including NRIP3, CYLD, CD9, ATF3 and OXTR were strongly induced by TSA alone." (PMID 18301774, 2008). "The oxytocin (OT) hypothalamic nonapeptide binds to various tumour types via the oxytocin receptor (OTR), a member of the seven transmembrane spanning family of G-protein-coupled receptors." (PMID 12942128, 2003). "Therefore, we hypothesized that OXTR may be involved in overactivation of the mTOR, TGF-β, and Wnt signaling pathways to promote tumor progression, which needs further study." (PMID 34877409, 2021).
tumor (continued). "Further, in formalin-fixed, paraffin-embedded OSCC tissues, OXTR immunoreactivity was found to be enriched in stromal fibroblasts from CAFWPOI 4-5 compared to CAFWPOI 1-3, but not in tumor cells." (PMID 36045118, 2022).
neurodevelopmental disorder (7 papers, 2017 to 2025). A behavioral and cognitive disorder with onset during the developmental period that involves impaired or aberrant development of intellectual, motor, or social functions. "Oxytocin is known to play critical roles in social and emotional behavior and a decrease in the expression of its receptor, OXTR is shown to be associated with social anxiety, a feature commonly observed in many neurodevelopmental disorders." (PMID 29311838, 2017). "However, the mechanisms underlying the dysregulation of OXT/OXTR signaling in neurodevelopmental disorders remain unclear." (PMID 37153633, 2023). "Increasing evidence warranted that aberrant OXT/OXTR signaling is an essential factor in the neuropathology of some neurodevelopmental disorders." (PMID 37153633, 2023). "The mechanisms underlying the dysregulation of OXT/OXTR signaling in neurodevelopmental disorders are not fully understood." (PMID 37153633, 2023). "Several mouse models of neurodevelopmental disorders present abnormalities in OXT release and/or OXTR distribution, providing a strong rationale for the use of OXT as a possible therapeutic agent." (PMID 36998737, 2023).
infection (4 papers, 2020 to 2021). The state of being infected such as from the introduction of a foreign agent such as serum, vaccine, antigenic substance or organism. "This is congruent with the higher relative expression ratio for the MePD oxytocin receptor post infection (∆∆Ct of means = 2.26; primer efficiency corrected the expression ratio obtained during 10,000 randomizations = 3.27)." (PMID 34832650, 2021). "The infection-induced increase in the oxytocin receptor in the MePD was not due to a generalized facilitation, as indicated by the lack of infection effects on mRNA abundance in the medial preoptic nucleus (t15 = 0.476, p = 0.641)." (PMID 34832650, 2021). "The infection did not significantly alter oxytocin receptor mRNA abundance in the PVN (t30 = 0.843, adjusted p = 0.647)." (PMID 34832650, 2021).
cardiovascular disease (3 papers, 2021 to 2024). "Such analyses allowed them to suggest possible mechanisms of the involvement of OXTR in the development of cardiovascular diseases." (PMID 36835321, 2023). "Therefore, it was concluded that the pathogenesis of cardiovascular diseases can be significantly influenced by the dysregulation of OXT production and OXTR expression, especially in such disorders as ischemia, hypoxia, inflammatory disturbances, pain, and stress conditions." (PMID 36835321, 2023).